ESM1 (endothelial cell specific molecule 1)
Diseases named in the same sentence as ESM1 in open-access papers (continued):
Sharing a sentence is not in itself a finding about the gene and the disease.
tumor (continued). "Tumor volume, lung metastasis, and tumorigenic molecules (VEGF-A, HIF-1α, MMP-9, ICAM-1, VCAM-1, and phospho-NF-κB and phospho-STAT-3) were significantly induced in mice injected with ESM-1-overexpressing 4T1 cells and greatly enhanced in those injected with ESM-1-overexpressing RT-R-4T1 cells." (PMID 32466580, 2020). "ESM1 overexpression in non-tumorigenic epithelial cells induces tumor formation in SCID mice." (PMID 27683113, 2016). "In addition, our results showed that ESM1 may act as a novel ligand of c-Met and activate the downstream MAPK signaling pathway after binding to c-Met on the surface of endothelial cells to promote the expression of pro-angiogenic molecules, thereby regulating tumor angiogenesis." (PMID 38201620, 2023). "Moreover, correlation analysis by the GEPIA database showed that the mRNA expression of ESM1 was evidently overexpressed in ACC tumors compared with that in normal ones (p < 0.005) but not significantly correlated with the tumor stage for ACC (p > 0.05)." (PMID 34858850, 2021). "in 2008 conducted a study on the role of ESM-1 in tumor progression in mice, showing that overexpression or systemic administration of endogenous non-glycosylated ESM-1 could delay the growth of HT-29 tumor cells." (PMID 34109132, 2021).
cancer (63 papers, 2006 to 2026). A tumor composed of atypical neoplastic, often pleomorphic cells that invade other tissues. "scRNA-seq analysis demonstrated that anlotinib reduced the proportions of myofibroblastic cancer-associated fibroblasts and ESM1+ endothelial cells, resulting in decreased angiogenesis." (PMID 40260248, 2025). "ESM1 has been implicated in the progression or metastasis of many malignancies, including pathogenic processes such as cell migration, invasion, and carcinoma angiogenesis." (PMID 37476182, 2023). "Recently, ESM1 has been implicated in the tumorigenesis and development of multiple cancers, including colorectal cancer, epithelial ovarian cancer, head and neck cancer, and prostate cancer." (PMID 35937390, 2022). "Endothelial cell-specific molecule 1 (ESM1) has been implicated as an oncogene in several types of cancer." (PMID 35937390, 2022). "ESM-1, overexpressed in several cancer types, is a potential cancer diagnostic and prognostic indicator." (PMID 36077661, 2022). "This article reviews the molecular and biological characteristics of ESM-1 in cancer, the underlying mechanisms, the currently clinical and pre-clinical applications, and potential therapeutic strategies." (PMID 34109132, 2021). "In this review, we discussed the multifaceted role of ESM-1 in some important cellular processes relevant to cancer and the underlying mechanisms." (PMID 34109132, 2021). "Full length RON activation cause increases in ESM1 (endocan) that has previously been associated with pro-angiogenic cytokine production and cancer metastasis and MMP3, which is associated with increased cell tumorigenicity." (PMID 27323855, 2016). "Endocan (or called Esm-1) has been shown to have tumorigenic activities and its expression is associated with poor prognosis in various cancers." (PMID 24340011, 2013). "Endothelial specific molecule-1 (ESM1) is implicated as an oncogene in multiple human cancers." (PMID 38626010, 2024). "ESM1 regulates critical signaling pathways in cancer development, including the AKT/NF-κB/Cyclin D1, PI3 K/Akt/mTOR, Wnt/β-catenin, DLL4-Notch, AKT/eNOS, and NF-κB/iNOS pathways." (PMID 40251641, 2025). "Mechanistic studies showed that activation of the Akt-dependent nuclear factor (NF)-κB/cyclin D1 pathway is critical for ESM1-modulated proliferation of multiple types of cancer." (PMID 39309430, 2024). "As a soluble sulfate skin proteoglycan, ESM1 is elevated in a variety of tumors and promotes progression of cancers, including proliferation, migration, invasion, angiogenesis, and drug resistance." (PMID 38720298, 2024). "Esm1 recombinant protein decreased T cell adhesion to ICAM-1, and cancer cell medium from Esm1 overexpression group inhibited T cell adhesion compared to Bcl6 knockout control group." (PMID 38956432, 2024). "As we advance, it is imperative that future research continues to dissect the multifaceted role of ESM1 in cancer biology, advocating for integrated studies across cancer types to solidify its position as a broad-spectrum molecular target in oncology." (PMID 38626010, 2024). "A summary of the models used for building a classifier capable of discriminating between cancer and normal samples based on the expression of seven features: ESM1, DHRS7C, OTOP3, AADACL2, LPHN3, GABRD, and LPAR1." (PMID 39484215, 2024). "This diverges from its previously established pro-cancerous role in other malignancies, indicating a more nuanced role for ESM1 in cancer biology." (PMID 38626010, 2024). "Of several pro-angiogenesis factors, endocan, also known as specific endothelial molecule (ESM-1), is sulfate proteoglycan and is released by both cancer cells and endothelial lineage in response to the hypoxic condition." (PMID 37337165, 2023). "Specifically, interference with ESM1 significantly diminished cancer cell proliferation, cell migration, and cell invasion in human SiHa and ME-180 cells after being transfected with siRNAs for 48 h or 24h." (PMID 37476182, 2023).
cancer (continued). "We also found that the migration and invasion molecular mechanism of ESM1 in OC progression was similar to that in these cancer types." (PMID 36594088, 2023). "Endocan, also known as endothelial specific molecule-1 (ESM-1), is a circulating PG secreted by several cell lines and involved in a plethora of pathological conditions, such as cancer and inflammatory diseases." (PMID 37175885, 2023). "As seen from analysis of the GSE161533 and TCGA database, ESM1 is notably elevated in 12 of 20 types of human cancer, including ESCA." (PMID 35937390, 2022). "TCGA pancancer gene expression analysis indicated that the expression of ESM1 is significantly elevated in 12 of 20 types of human cancer." (PMID 35937390, 2022). "In recent years, substantial investigations have focused on the relationship between ESM-1 and cancer." (PMID 34109132, 2021). "Our study showed that MBZ significantly induced DNA damage, cell cycle arrest, and downregulation of cancer stem cell markers CD44 and OCT3/4, and cancer progression-related ESM-1 protein expression in TNBC and RT-R-TNBC cells." (PMID 34500557, 2021). "In the current essay, the assessment in human ACC samples and multiple public cancer databases suggested that ESM1 was significantly overexpressed in ACC patients." (PMID 34858850, 2021). "A broad array of genetic knockdown experiments validated the potential of ESM-1 as a powerful target for clinical evaluation in the treatment of cancer." (PMID 34109132, 2021). "Studies have shown that ESM-1 is aberrantly expressed in a myriad of diseases, such as cancer, vascular disorder, and inflammation." (PMID 34109132, 2021). "As a kind of soluble DS proteoglycan, ESM-1 plays an important role in cancer initiation and progression." (PMID 34109132, 2021). "For instance, endothelial cell-specific molecule-1 (ESM-1) is an oncogene factor that is upregulated in various cancers." (PMID 32784981, 2020). "ESM-1 is a secreted proteoglycan dermatan produced by ECs, and as mentioned in the introduction, a high level of ESM-1 secretion has been found in various cancers." (PMID 32466580, 2020). "Endocan, also known as endothelial cell specific molecule-1 (ESM1), is a 50 kDa soluble proteoglycan which is frequently overexpressed in many cancer types." (PMID 31073279, 2019). "Because genetic instability such as gene copy number alteration is a general potential factor affecting gene expression in cancers, we therefore also examined the relationship between ESM1 copy number and gene expression in 514 common HNSCC samples." (PMID 31073279, 2019). "Previous studies indicated that ESM-1 was over-expressed in various malignant tumors tissue including NSCLC." (PMID 28514746, 2017). "To investigate the role of ESM-1 in the regulation of cancer malignancy by HULC, we transfected the ESM-1 expression plasmid into HULC-silenced U87MG and U251 cells to observe the reversed effect of HULC silencing in a subsequent experiment." (PMID 26894862, 2016). "This region of chromosome 11 contains several genes, most notably CyclinD1 and ESM1/Cortactin, which are frequently overexpressed, mainly through amplification, in a variety of human cancers." (PMID 16552434, 2006). "Both types of cancer cells were injected into the brains of WT and Esm1 KO mice." (PMID 39773984, 2025). "Our research indicates that ESM1 is pivotal in cancer metabolic reprogramming." (PMID 40251641, 2025). "Furthermore, we recently showed that ESM1 maintains cancer stemness and promotes metastasis of prostate cancer via coordinating the Wnt/β-catenin pathway." (PMID 39309430, 2024). "In addition to the in vitro 2D and 3D culture systems, we further utilized an in vivo xenograft model to assess the importance of secreted ESM1 in facilitating cancer development." (PMID 39309430, 2024).
cancer (continued). "ESM1 could also regulate these molecular signaling pathways in cancer development and progression, such as the AKT/NF-kappaB/Cyclin D1 pathway 20, Wnt/β-catenin pathway 18, DLL4-Notch pathway 21, AKT/eNOS 22 and NFkB/iNOS signaling." (PMID 36594088, 2023). "ESM1 has been demonstrated to be upregulated in multiple cancer types, but the oncogenic mechanism by which ESM1 promotes OC is still largely unknown." (PMID 36594088, 2023). "Furthermore, ESM1 overexpression promoted carcinoma angiogenesis and CSCC progression through the VEGF/ERK signaling pathway." (PMID 37476182, 2023). "Furthermore, GSEA analysis revealed that the ESM1 high expression group was significantly enriched in carcinoma angiogenesis and the VEGFα signaling pathway." (PMID 37476182, 2023). "ESM1 was first discovered as a soluble dermatan sulfate proteoglycan secreted by endothelial cells and then gradually reported to play a vital role in a variety of cancers." (PMID 36117773, 2022). "In a previous study, we found that MBZ alone had anticancer effects in RT-resistant TNBC by inducing apoptosis and cell cycle arrest, suppressing the expression of cancer stem cell markers (CD44 and OCT3/4), and inhibiting cancer progression-related ESM-1 proteins." (PMID 36555137, 2022). "Further, we found that mebendazole (MBZ), a benzimidazole derivative, exhibited the most effective anticancer effects in TNBC through inducing DNA damage, cell cycle arrest, and downregulating cancer stem cell markers CD44 and OCT3/4 and cancer progression-related ESM-1 protein expression." (PMID 36555137, 2022). "ESM1 is significantly elevated in 12 of 20 types of human cancer." (PMID 35937390, 2022). "More recently, studies have found that ESM1 could participate in various physiological processes in cancer cells, including cell proliferation, angiogenesis, migration, and invasion, as well as therapy resistance." (PMID 36522312, 2022). "Moreover, aberrant ESM1 expression is associated with multiple diseases, including inflammation, vascular disorders, and cancer.ESM1 is upregulated in a broad spectrum of cancers, often correlated with a poor prognosis." (PMID 36522312, 2022). "In future studies, combining gene expression and serum levels of ESM1 together to predict cancer prognosis could be a potential research direction." (PMID 35937390, 2022). "In bladder cancer, ESM1 promoted cancer metastasis by positively regulating VEGF-A/VEGFR-2 axis." (PMID 36522312, 2022). "Recently, ESM1 has been shown to have a high expression level in numerous types of cancer, suggesting that it may be a potential biomarker for the diagnosis and treatment of different cancers." (PMID 35937390, 2022). "ESM1 is a potential prognostic biomarker in corresponding cancer." (PMID 35937390, 2022). "Given the significant role of ESM-1 in cancers, it may be a potential target in cancer treatment, and the inhibitors targeting ESM-1 are urgently needed." (PMID 34109132, 2021). "Emerging evidence indicates that ESM-1 expression is elevated in a broad spectrum of cancers." (PMID 34109132, 2021). "Herein, we have attempted to shed light on the unique role of ESM-1 in cancers." (PMID 34109132, 2021). "ESM-1 protein is aberrantly expressed in many cancers, including hematologic and solid tumors." (PMID 34109132, 2021). "In addition, thoroughly understanding the relationship between ESM-1 expression and the subsistent clinicopathological characters of cancers is helpful for combining diagnosis." (PMID 34109132, 2021). "Herein, we propose that ESM-1 is a new therapeutic target for cancer therapy." (PMID 34109132, 2021). "As ESM-1 is a secreted protein, it is a potential marker for cancer." (PMID 34109132, 2021). "Since ESM-1 are upregulated in many cancers, interference with ESM-1 by miRNA may be a potential therapeutic strategy." (PMID 34109132, 2021).
cancer (continued). "Additionally, ESM-1 is down-regulation after exosomal miR-9-3p treatment, and the cancer progression and metastasis are both prevented in xenograft model of bladder cancer in mice." (PMID 34109132, 2021). "Therefore, in this study, we also examined the role of ESM-1 in cell adhesion molecule expression, the adhesion of cancer cells to ECs, and metastasis-related factors such as MMP-9 and VEGF-A." (PMID 32466580, 2020). "ESM-1 is regarded as a marker of angiogenesis, an important factor in the progression of cancer." (PMID 28533735, 2017). "For instance, patients who do not respond to radioactive iodine due to dedifferentiation of cancer cells or those who experience significant side effects from standard treatments might benefit from a more personalized approach that includes ESM1-targeted therapies." (PMID 38626010, 2024). "However, it is too early to consider that ESM-1 in circulation may be a beneficial marker for cancers in humans." (PMID 36595996, 2022). "In addition, ESM-1 is a biomarker for diagnosis and prognosis of cancers." (PMID 34109132, 2021). "Considering the over-expression of ESM-1 in carcinoma endothelial cells and the vital roles of ESM-1 in cell adhesion, proliferation, and angiogenesis, it is reasonable that ESM-1 in pleural fluid may be a novel biomarker for pleural or distant metastasis of NSCLC." (PMID 28514746, 2017). "Western blot (WB), Polymerase Chain Reaction (PCR), and immunofluorescence (IF) were employed to evaluate the effects of lactate on the expression of ESM1, Akt1, and Cyclic GMP-AMP Synthase (cGAS) pathway-related proteins in cancer cells." (PMID 41930148, 2026). "Endothelial cell-specific molecule 1 (ESM1), a secreted glycoprotein, is elevated in various cancers, but its role in GC remains controversial." (PMID 39309430, 2024). "Therefore, the development of ESM-1 targeting drugs may open up a new chapter in cancer therapy." (PMID 38954708, 2024). "Based on our bioinformatics analysis and experimental validation, we confirmed that ESM1 could accelerate OC carcinogenesis (proliferation, apoptosis, metastasis, and angiogenesis) via the Akt/mTOR pathway, which has been demonstrated to be a significant cancer-promoting signaling pathway." (PMID 36594088, 2023). "Therefore, targeting ESM-1 could be a promising strategy to treat inflammation and cancer." (PMID 34109132, 2021). "In the second week after cancer cell inoculation, plasma concentrations of SDC-1, ESM-1 and sVCAM-1 diminished to values observed in control animals, while plasma concentration of Angpt-2 rose from 146.17±8.31 to 228.93±8.57 pmol/ml." (PMID 30683749, 2019). "In the first week after cancer cell inoculation, marked glycocalyx disruption (SDC-1 and ESM-1) and notable activation of pro-inflammatory adhesion molecules [soluble VCAM-1 (sVCAM-1)] were detected." (PMID 30683749, 2019). "Therefore, ESM-1 may be useful as a therapeutic cancer target." (PMID 31073279, 2019). "The overexpression of ESM1 in HNSCC and other cancers was also confirmed based on paired analysis of TCGA data." (PMID 31073279, 2019). "ESM1, one of the most up-regulated genes in the NGFR overexpressing MOC2T cells, was of particular interest given its known role in cancer progression." (PMID 27683113, 2016). "Using machine learning algorithms, including RF, SVM, GBM (XGBoost), and DT, the genes CDH3, DKC1, ESM1, MUSTN1, RCC2, TMT1A, and VEGFD were selected as key features from the tissue dataset to best discriminate between cancer and control samples and were used to design the predictive model." (PMID 40425785, 2025). "Additionally, angiopoietin-2 (ANGPT2) was found to be highly correlated with ESM1 and interplayed with Akt to induce the EMT and cancer progression." (PMID 39309430, 2024). "In addition, angiopoietin-2 (ANGPT2) was highly correlated with ESM1 and interplayed with Akt to induce the EMT and cancer progression in GC." (PMID 39309430, 2024).
cancer (continued). "A feature space of just seven biomarkers, namely ESM1, DHRS7C, OTOP3, AADACL2, LPHN3, GABRD, and LPAR1, was sufficient to optimize a RandomForest model that achieved > 98% balanced accuracy (and performant recall) of cancer vs. normal on external validation." (PMID 39484215, 2024). "ESM1 could induce proliferation and migration via VEGF to induce lymphangiogenesis and cancer metastasis." (PMID 36594088, 2023). "We also examined ESM1 expression in 71 primary cancer tissues without PM and 30 primary cancer tissues with PM and found that primary tissues with PM had a higher ESM1 expression." (PMID 38201620, 2023). "The results showed that the median expression level of ESM1 in cancer tissues was 1.37 (0.40-6.44), and in adjacent normal tissue, it was 0.34 (0.12-1.56) (p = 0.01)." (PMID 35937390, 2022). "ESM1 is known to be upregulated by inflammatory cytokines (IL-1β, TNF-α, and IFN-γ) and proangiogenic factors (VEGF-A and VEGF-C) and PI3K dependent pathway in cancer cell or endothelial cell." (PMID 32466580, 2020). "Second, serum ESM-1 levels are also elevated in other types of cancers and thus are not specific for RCC." (PMID 29416643, 2018). "Notably, we also used in vitro growth curve to show that overexpression of Esm-1 did not affect cancer cell proliferation." (PMID 38956432, 2024). "Interestingly, ESM-1 is only enhanced in triple negative breast cancer (TNBC), the most aggressive and easily metastatic breast cancer subtype, and its expression is positively correlated with the malignancy of cancer." (PMID 34109132, 2021). "Several other candidate genes were found to be undetectable in whole blood, while most of the genes that were detectable (EGLN3, CAV2, ESM1, TMEM45A, NOL3, FABP7) did not exhibit significant dysregulation in expression between cancer and healthy PAXgene samples." (PMID 32013938, 2020).
cardiovascular disease (5 papers, 2018 to 2023). "Serum biomarkers of endothelial cell activation such as E-Selectin and endothelial cell-specific molecule-1 (ESM-1) could aid in early detection of PLWH at a risk of cardiovascular diseases." (PMID 37161496, 2023). "Endothelial cell-specific molecule-1 (ESM-1) has emerged as a potential biomarker for cardiovascular disease in humans." (PMID 35790968, 2022). "There is limited literature on the serum concentration of ESM-1 in PLWH in Sub-Saharan African, but a meta- analysis showed that elevated serum ESM-1 levels were significantly associated with cardiovascular diseases and could be one of the risk factors for cardiovascular diseases." (PMID 37161496, 2023).